PINK1 (PTEN induced kinase 1)
Diseases named in the same sentence as PINK1 in open-access papers (continued):
Sharing a sentence is not in itself a finding about the gene and the disease.
testicular germ cell tumor (2 papers, 2020 to 2025). A germ cell tumor arising from the testis. "The PINK1 methylation pattern was significantly anti-correlated with the gene’s expression in pheochromocytoma and paraganglioma tumors (PCPG), uveal melanoma (UVM), KIRC, and testicular germ cell tumors (TGCT)." (PMID 39859167, 2025).
viral myocarditis (2 papers, 2023 to 2025). Myocarditis that is caused by an infection with a viral agent. "The pathway terms appearing in both LRRK2 and PINK1 enrichment results are “tuberculosis”, “viral myocarditis”, and “IL-17 signalling pathway”, although mainly not among the statistically significant results after adjustment for multiple hypothesis testing." (PMID 40650986, 2025).
acute liver failure (1 paper, 2018). Rapid deterioration of liver function causing encephalopathy and coagulopathy. "The inhibition of PINK1 appears to correlate with upregulation of ER stress, which contributes to liver inflammation and hepatotoxicity in acute liver failure." (PMID 30333475, 2018). "During acute liver failure induced by LPS/D-GalN, CO induced the levels of mitochondrial PINK1 and Parkin, and PGC1α-mediated NRF1 and TFAM gene expressions, which could lead to promotion of mitochondrial turnover and biogenesis." (PMID 30333475, 2018).
age (1 paper, 2018). A temporal measurement of the time period elapsed since an identifiable point in the life cycle of an organism. "Thus, PINK1 and parkin appear to be particularly important for mitophagy during aging, which may explain why loss of these proteins in patients causes an age-dependent neurodegenerative disease rather than a congenital or developmental disorder." (PMID 29809156, 2018).
anemia (1 paper, 2013). A reduction in the number of red blood cells, the amount of hemoglobin, and/or the volume of packed red blood cells. "This also raises the possibility that parkin and PINK1 function in a programed mitophagy pathway, although it would be unlikely to involve RBCs, as one would then expect parkin- or PINK1-associated PD patients to present with anemia." (PMID 23882257, 2013).
aneurysm (1 paper, 2021). Bulging or ballooning in an area of an artery secondary to arterial wall weakening. "Given its significance in mitochondrial quality control, we propose that disturbed mitochondrial dynamics contributes to the pathogenesis of AAA and underlines the central role of the PINK1/PARKIN pathway during the pathogenesis of aneurysms based on currently available evidence." (PMID 34221126, 2021).
basal cell carcinoma (1 paper, 2012). A carcinoma involving the basal cells. "The possible link between PD and basal cell carcinoma cannot be ruled out in light of the finding that several PD genes such as Parkin, Pink1 and Dj-1 have been associated with certain cancers." (PMID 22563483, 2012).
brain inflammation (1 paper, 2011). "On the other hand, GSK-3β also functions as a negative regulator of pro-inflammatory cytokine expression and decreased GSK-3β expression may render Pink1−/− mice more vulnerable to TNF-α, IL-1β and LPS-induced brain inflammation." (PMID 21249202, 2011).
breast invasive carcinoma (1 paper, 2020). "However, deletion of PINK1 was associated with substantially higher CD4+ T cell, neutrophil and dendritic cell counts in breast invasive carcinoma." (PMID 33244455, 2020).
carotid atherosclerosis (1 paper, 2021). A thickening and loss of elasticity of the walls of carotid arteries that occur with formation of atherosclerotic plaques. "Previously, we found elevated Pink1 in the plaque cap of human carotid atherosclerosis samples." (PMID 34576157, 2021).
chronic liver failure (1 paper, 2022). Liver failure that develops slowly and gradually for some time, possibly for years, often as the result of cirrhosis, or malnutrition. "This suggests that PINK1 inhibits apoptosis through AKT activation via mTORC2 to protect from acute-on-chronic liver failure." (PMID 35461334, 2022).
chronic myeloid leukemia (1 paper, 2022). "Western blot results confirmed that UNC13B may modulate the apoptosis and proliferation of arsenic trioxide-resistant chronic myeloid leukemia cells through the mediation of MAP3K7, CDK4, and PINK1." (PMID 35707364, 2022).
colorectal adenocarcinoma (1 paper, 2023). The most common type of colorectal carcinoma. "Second, the study is limited to a specific subset of CRC and the determination of PINK1 immunoexpression in non-metastatic colorectal adenocarcinomas was not addressed." (PMID 37047483, 2023).
deafness (1 paper, 2025). An inherited or acquired condition characterized by the complete loss of the ability to hear from one or both ears. "In this study, we investigated the mechanism underlying mitochondrial tRNA processing defects arising from the deafness-associated m.7516delA mutation reprogramed mitochondrial and cellular homeostasis via activating both ISR and PINK1/Parkin mitophagy pathways." (PMID 40473214, 2025).
developmental delay (1 paper, 2024). "The human CDK19 patients show some similar but milder phenotypes, including developmental delay, seizure, and hypotonia, suggesting that the function of DNM1L is not fully dependent on Pink1 and CDK19." (PMID 38637532, 2024).
E. coli infection (1 paper, 2021). "Besides, E. coli infection inhibited mitophagy while LGR-1 pretreatment augmented PINK1/Parkin–mediated mitophagy activation, which further blocked ROS generation." (PMID 34594329, 2021).
edema (1 paper, 2025). An abnormal accumulation of fluid beneath the skin, or in one or more cavities of the body. "Heparin precisely targets this pathway by upregulating Epsa1, restoring Idh2 activity, and stabilizing Hif3a, thereby enhancing Pink1/Parkin-mediated mitophagy to eliminate impaired mitochondria, suppress sustained inflammatory activation, and ultimately reduce neuronal apoptosis and cerebral edema." (PMID 41585220, 2025).
embryonal carcinoma (1 paper, 2016). A non-seminomatous malignant germ cell tumor characterized by the presence of large germ cells with abundant cytoplasm resembling epithelial cells, geographic necrosis, high mitotic activity, and pseudoglandular and pseudopapillary structures formation. "Although PINK1+/+- and PINK1−/−-iPSCs gave rise to teratomas composed of various recognizable tissue elements, we observed striking differences in the embryonal carcinoma (EC)-like component of poorly differentiated, primitive-appearing, blast-like teratocarcinoma stem cells." (PMID 27295498, 2016).
encephalitis (1 paper, 2024). An acute inflammatory process affecting the brain parenchyma. "Further, in vitro experiments in the anti-NMDAR encephalitis cell model showed that IgG-positive CSF exposure led to a significant downregulation of PINK1, PARKIN, and LC3B, indicating a deficiency in mitophagy." (PMID 38745240, 2024).
energy (1 paper, 2024). "We found decreased levels of ROS, Aβ1-40, and Aβ1-42 and increased levels of mitochondrial membrane potential and ATP, which may be associated with PINK1 decreasing oxidative stress and improving energy metabolism disorders in APP/PS1-N2a cells." (PMID 38731398, 2024).
energy metabolism disorder (1 paper, 2021). "In summary, we show that H2O2 induced oxidative stress caused intestinal epithelial barrier damage and mitochondrial energy metabolism disorder and activated PINK1-Parkin-mediated mitophagy and AMPK signaling pathways." (PMID 34943113, 2021).
esophageal adenocarcinoma (1 paper, 2020). A malignant tumor with glandular differentiation arising predominantly from Barrett mucosa in the lower third of the esophagus. "Notably, we newly identified PINK1 as a protective prognostic factor in ESCA (esophageal adenocarcinoma) (OS: log rank P = 0.039)." (PMID 33244455, 2020).
familial hypercholesterolemia (1 paper, 2023). An inheritable form of hyperlipidemia, in which there are excess lipids in the blood. "For prevalent MI we identified FYTTD1 (down-regulated in familial hypercholesterolemia) and PINK1 (linked to cardiac tissue homeostasis and ischemia–reperfusion injury)." (PMID 38062110, 2023).
focal segmental glomerulosclerosis (1 paper, 2023). A renal disorder characterized by sclerotic lesions in the glomeruli. "Our previous study showed that Mfn2 deficiency participates in podocyte injury in a focal segmental glomerulosclerosis (FSGS) animal model by inhibiting Pink1/Parkin-associated mitophagy." (PMID 36998021, 2023).
functional dyspepsia (1 paper, 2024). "XSLJZD can improve gastrointestinal motility disorder in functional dyspepsia with spleen deficiency syndrome, which was related to reconstruction of the mitochondrial quality control system by restraining PINK1/Parkin-mediated mitophagy and division." (PMID 38335441, 2024).
gastric tumor (1 paper, 2023). "Among autophagy genes in the Reactome database, PRMT1 was negatively correlated with genes such as ATG9A, DYNC1H1, EPAS1, PINK1, TSC1, TUBB6, and ULK1 in gastric tumor tissues (STAD-TCGA) and positively correlated with HMMR, ESCO2, CHAC2, and NUDT6 (STAD-TCGA)." (PMID 37564212, 2023).
glomerulosclerosis (1 paper, 2023). A hardening of the kidney glomerulus caused by scarring of the blood vessels. "To clarify whether the effect of PINK1 knockout on the other cell types contributed to the change of aging, we also compared glomerulosclerosis and podocyte loss according to Pink1 knockout." (PMID 37183600, 2023). "The glomerular scoring for glomerulosclerosis significantly increased in the 24‐month‐old mice, but there was no significant change between in 24‐month Pink1+/+ and Pink1−/− mice." (PMID 37183600, 2023).
Glucose intolerance (1 paper, 2023). Glucose intolerance (GI) can be defined as dysglycemia that comprises both prediabetes and diabetes. "Pink1-KO mice did not exhibit reduced β-cell function or glucose intolerance, although NADH generation and mitochondrial potential after glucose challenge were reduced in Pink1-KO β-cells." (PMID 37653033, 2023).
glucose metabolic disorders (1 paper, 2023). "In vitro experiments further suggested that the hepatic glucose metabolic disorder induced by TAC might be mediated by PINK1." (PMID 37151651, 2023). "Proper inhibition of PINK1 activation is of help to prevent and alleviate TAC-induced glucose metabolic disorders." (PMID 37151651, 2023).
hepatitis C (1 paper, 2024). "Several viral proteins, such as NS5A encoded by the hepatitis C and classical swine fever viruses, trigger ROS production, causing PINK1/Parkin-dependent mitophagy for viral replication." (PMID 38184594, 2024).
high altitude pulmonary edema (1 paper, 2024). "VD3 treatment decreased the expression of PINK1 (2.95 ± 0.51 vs 1.72 ± 0.35) and Parkin (2.76 ± 0.19 vs 0.49 ± 0.17) in the lung of high-altitude pulmonary edema rats." (PMID 38166725, 2024).
hypersensitivity pneumonitis (1 paper, 2019). Hypersensitivity pneumonitis (HP) is a pulmonary disease with symptoms of dyspnea and cough resulting from the inhalation of an antigen to which the subject has been previously sensitized. "Free mtDNA was found elevated in other ILDs with low expression of PINK1 including hypersensitivity pneumonitis and autoimmune interstitial lung diseases." (PMID 31170232, 2019).
infarction (1 paper, 2017). A localised pathological necrosis of tissue resulting from obstruction of the blood supply usually by a thrombus, an embolus, or vascular torsion. "However, PINK1 has been shown to be a downstream target of FOXO3a, thus suggesting the possibility that resveratrol and Longevinex may induce PINK1 expression via FOXO3a activation to subsequently facilitate Parkin recruitment to the mitochondria in the infarction area." (PMID 28626500, 2017).
infiltrating ductal carcinoma (1 paper, 2024). "Notably, the expression of PINK1.AS, OIP5.AS1, HID.AS1, and MAPT.AS1 was statistically higher in the infiltrating ductal carcinoma subtype." (PMID 38326441, 2024).
influenza (1 paper, 2022). An acute viral infection of the respiratory tract, occurring in isolated cases, in epidemics, or in pandemics; it is caused by serologically different strains of viruses (influenzaviruses) designated A, B, and C, has a 3-day incubation period, and usually lasts for 3 to 10 days. "In conclusion, the newly identified Lnc‐PINK1‐2:5 isoform is an anti‐influenza lncRNA acting through the upregulation of TXNIP gene expression." (PMID 35201667, 2022). "In conclusion, Lnc‐PINK1‐2:5 is an anti‐influenza lncRNA acting through the upregulation of TXNIP." (PMID 35201667, 2022).
insomnia (1 paper, 2025). A sleep disorder characterized by difficulty in falling asleep and/or remaining asleep. "The results of this study showed that PINK1, Parkin, and LC3 expression was increased and p62 expression was decreased in insomnia rats, and senegenin intervention decreased the expression of PINK1, Parkin, and LC3 and increased the expression of p62." (PMID 39380353, 2025). "Therefore, in this study, GAD67 lentivirus was transfected at the epigenetic level in vitro and in vivo to explore the mechanism of senegenin in regulating insomnia through the GAD67‐mediated Keap1/Nrf2/Parkin/PINK1 pathway." (PMID 39380353, 2025). "Therefore, considering better safety, we chose GAD67 expression in viral vectors to explore how senegenin mediates the Keap1/Nrf2/Parkin/PINK1 pathway to regulate insomnia through GAD67." (PMID 39380353, 2025). "We measured GAD67 expression levels in insomnia patients and evaluated the expression levels of GAD67 and Keap1/Nrf2/Parkin/PINK1‐related cytokines following GAD67 lentiviral transfection in PC12 cells and in rat models." (PMID 39380353, 2025). "GAD67 is negatively correlated with sleep–wake rhythm and can regulate Keap1/Nrf2/Parkin/PINK1 expression, and senegenin can further regulate Keap1/Nrf2/Parkin/PINK1 by mediating GAD67, thus playing a regulatory role in the development of insomnia." (PMID 39380353, 2025). "In conclusion, GAD67 negatively regulates insomnia, and senegenin can regulate insomnia by mediating the expression of cytokines in the GAD67‐regulated Keap1/Nrf2/Parkin/PINK1 pathway." (PMID 39380353, 2025).
iron deficiency (1 paper, 2020). "The bars hatched in black within the first panel confirm the knockout of Pink1 in the 3 MEF lines and reproduce the high transcriptional induction of Pink1 after iron deficiency." (PMID 33023155, 2020).
iron overload (1 paper, 2020). "The impact of PINK1 mutations in mouse and patient cells was pronounced only after iron overload, causing hyperreactive expression of ribosomal surveillance factor Abce1 and of ferritin, despite ferritin translation being repressed by IRP1." (PMID 33023155, 2020).
ischemia reperfusion injury (1 paper, 2022). Adverse functional, metabolic, or structural changes in ischemic tissues resulting from the restoration of blood flow to the tissue (reperfusion), including swelling; hemorrhage; necrosis; and damage from free radicals. "Under ischemia-reperfusion injury (IRI), melanin restores the engagement of VDAC1 with hexokinase II (HKII) to restrict mitochondrial fission, which inhibits mPTP opening and PTEN induced kinase 1 (PINK1)/PARKIN activation, eventually blocking mitophagy-mediated cell death." (PMID 36588561, 2022).
ischemic cardiomyopathy (1 paper, 2024). Ischemic cardiomyopathy is a cardiomyopathy in which a weakness in the muscle of the heart due to inadequate oxygen delivery to the myocardium with coronary artery disease being the most common cause. "Recent studies demonstrate that hydrogen exerts these effects in ischemic cardiomyopathy-induced cardiomyocytes via PINK1/Parkin-mediated mitophagy." (PMID 39737905, 2024). "In TCM patients, significant changes in PINK1 protein expression related to mitophagy were identified, highlighting the potential of TCM treatments for ischemic cardiomyopathy." (PMID 39737905, 2024). "Interestingly, melatonin-induced cardioprotection in hypoxia-induced ischemic cardiomyopathy is independent of changes in the PINK1/Parkin pathway." (PMID 39737905, 2024).
juvenile-onset Parkinson disease (1 paper, 2025). "Some other mutations in autophagy genes regardless of ATGs assumed to be associated with autosomal recessive or sporadic juvenile-onset Parkinson's disease; for instance, we can mention PARK2/Parkin and PARK6/PINK1." (PMID 40093192, 2025).
Listeria monocytogenes infection (1 paper, 2024). "Additionally, we examined the protein and mRNA levels of LC3B, PINK1/Parkin, and Bax/Bcl-2 in goat uterine tissue to explore the influence of Listeria monocytogenes infection on cell autophagy and apoptosis." (PMID 39220769, 2024). "The increase in LC3B and the LC3BII/LC3BI ratio likely indicates heightened autophagic activity, whereas the opposing regulation of PINK1 and Parkin suggests that the control of autophagy by Listeria monocytogenes infection is not unidirectional." (PMID 39220769, 2024). "However, PINK1 was positively expressed in the endothelial cells within the stroma, differing from LC3B and Parkin, suggesting that Listeria monocytogenes infection may lead to differential regulation of autophagy-related proteins across various cell types." (PMID 39220769, 2024).
memory (1 paper, 2024). The activities involved in the mental information processing system that receives (registers), modifies, stores, and retrieves informational stimuli. "The PINK1-dependent pathway activates mitophagy, increases the clearance of extracellular Aβ plaques, inhibits neuroinflammation, relieves tau hyperphosphorylation, and reverses memory impairment." (PMID 38731398, 2024).
monoclonal gammopathy of undetermined significance (1 paper, 2020). "Using three publicly available datasets, we analyzed the mRNA level of PINK1 and PARK2 in bone marrow CD138+ cells of patients with monoclonal gammopathy of undetermined significance (MGUS) or MM." (PMID 32154065, 2020).
motor neuron disease (1 paper, 2017). "It was recently demonstrated that the downregulation of Ataxin-2, a lipid-storage factor and mTOR-repressor upstream from PINK1, may postpone death in a mouse model of motor neuron disease from 20 to over 300 days." (PMID 28768533, 2017).
Myocardial fibrosis (1 paper, 2025). "Third, the mechanism underlying exercise-based CR remained unelucidated, particularly PINK1/Parkin or FUNDC1-dependent mitophagy, mitochondrial quality control, mitochondria-related oxidative stress, as well as their mechanisms of interaction in myocardial fibrosis." (PMID 40741139, 2025).
myopia (1 paper, 2025). "In summary, using clinical samples from patients with high myopia, we further revealed that the miR-342-5p/PINK1/Parkin axis may be involved in the development of high myopia and that mitophagy may be inhibited in RGCs in high myopia." (PMID 39894836, 2025). "EA treatment can reduce RGC damage and slow myopia progression in guinea pigs with FDM, which may be related to the activation of the mitophagy-associated PINK1/Parkin signaling pathway through lncRNA-XR_002789763.1 sponging of miR-342-5p in these cells." (PMID 39894836, 2025). "We suggest that lncRNA-XR_002789763.1 may be involved in the occurrence and development of myopia by regulating RGC damage through the miR-342-5p/PINK1 pathway." (PMID 39894836, 2025). "EA treatment might regulate lncRNA-XR_002789763.1/miR-342-5p axis and activate the mitophagy-related PINK1/Parkin signaling pathway, and promote Mfn2 ubiquitination, thereby alleviating RGC damage and delaying myopia progression in guinea pigs." (PMID 39894836, 2025). "EA treatment might regulate lncRNA-XR_002789763.1/miR-342-5p axis and activate the mitophagy-related PINK1/Parkin signaling pathway, and promote Mfn2 ubiquitination, thereby alleviating RGC damage and delaying myopia progression." (PMID 39894836, 2025).
neuroendocrine tumors (1 paper, 2023). "Mutations in the PARK6 gene (PINK1) have been observed in neuroendocrine tumors, suggesting that changes in mitophagy contribute to the development of specific tumor types." (PMID 38067169, 2023).